NDUFS3 (NADH:ubiquinone oxidoreductase core subunit S3)
Description:
Core subunit of the mitochondrial membrane respiratory chain NADH dehydrogenase (Complex I) which catalyzes electron transfer from NADH through the respiratory chain, using ubiquinone as an electron acceptor. Essential for the catalytic activity and assembly of complex I.
Synonyms: CI-30; MC1DN8
Tractability: Small molecule: an approved drug acts on it; a structure with a bound ligand is known. Antibody: UniProt places it where antibodies can reach, with high confidence. PROTAC: ubiquitination databases record sites on it; its protein half-life has been measured.
Target class: Enzyme; Oxidoreductase
Gene: Protein-coding gene on chromosome 11 (47,565,336 to 47,584,565, forward strand). Ensembl gene ENSG00000213619.
Subcellular location: Mitochondrion inner membrane
Subcellular location (Human Protein Atlas): Mitochondria; Nuclear bodies; Principal piece
Pathways (Reactome):
Metabolism: Complex I biogenesis; Respiratory electron transport
Metabolism of proteins: Mitochondrial protein degradation
Signal Transduction: RHOG GTPase cycle
Gene Ontology:
Molecular function: NADH dehydrogenase (ubiquinone) activity; NADH dehydrogenase activity; protein binding; electron transfer activity; oxidoreductase activity, acting on NAD(P)H
Biological process: mitochondrial electron transport, NADH to ubiquinone; mitochondrial respiratory chain complex I assembly; reactive oxygen species metabolic process; substantia nigra development; aerobic respiration; proton motive force-driven mitochondrial ATP synthesis; proton transmembrane transport
Cellular component: mitochondrial inner membrane; mitochondrial membrane; mitochondrion; respiratory chain complex I; mitochondrial matrix
Genetic constraint (gnomAD): Loss-of-function variants: 19 observed, 32.57 expected, observed/expected ratio (o/e) 0.58, 90% interval 0.41 to 0.86. The upper end of that interval is the gene's LOEUF score, 0.86, which puts it in group 3 of 6, group 1 being the genes least tolerant of losing a copy. Missense variants: 331 observed, 354.72 expected, observed/expected ratio (o/e) 0.93, 90% interval 0.85 to 1.02. Synonymous variants: 153 observed, 142.57 expected, observed/expected ratio (o/e) 1.07, 90% interval 0.94 to 1.23.
Gene-disease validity (ClinGen):
ClinGen rates the evidence that NDUFS3 causes each of these diseases.
Leigh syndrome (autosomal recessive): Moderate. A progressive neurological disease defined by specific neuropathological features associating brainstem and basal ganglia lesions.
mitochondrial disease (autosomal recessive): Moderate.
Homologues: Orthologues: chimpanzee NDUFS3 (99% identical), macaque NDUFS3 (97% identical), pig NDUFS3 (90% identical), rabbit NDUFS3 (90% identical), mouse Ndufs3 (87% identical), rat Ndufs3 (85% identical), guinea pig NDUFS3 (84% identical), tropical clawed frog ndufs3 (73% identical), zebrafish ndufs3 (71% identical), Drosophila melanogaster ND-30 (62% identical), Caenorhabditis elegans nuo-2 (52% identical).
Diseases named in the same sentence as NDUFS3 in open-access papers:
NDUFS3 is named in the same sentence as 73 diseases in open-access papers, as found by Europe PMC text mining. Sharing a sentence is not in itself a finding about the gene and the disease. The quoted sentences say what the papers report.
breast carcinoma (10 papers, 2013 to 2025). "Studies have shown that NDUFS3 deficiency is associated with mitochondrial dysfunction in breast cancer and chromophobe renal cell carcinomas." (PMID 40404919, 2025). "NDUFS3 knockdown has been shown to significantly decrease tumour cell proliferation, and overexpression of NDUFS3 is associated with breast cancer invasiveness." (PMID 30886710, 2019). "Low expression levels of NDUFS3 were detected in kidney cancer, serous ovarian cancer and human mammary carcinoma (HMC-1)." (PMID 40404919, 2025). "Of note, inhibition of mitochondrial complex I activity by reduction of core subunit NDUFS3 or NDUFV1 as well as accessory subunit NUDFB9 has been found to enhance the aggressive potential of breast cancer." (PMID 37644092, 2023). "One of them is NDUFS3, a potential biomarker to discriminate invasive from normal breast cancer, whose expression is controlled by the CLOCK gene." (PMID 32295075, 2020). "In addition, knockdown of NDUFS3 expression promotes aerobic glycolysis in breast cancer and renal carcinoma." (PMID 40404919, 2025). "We also observed that the expressions of GRIM-19, NDUFS3, and ECM elements were correlated with invasive capabilities of breast cancer cell lines." (PMID 23630608, 2013). "However, NDUFV2, NDUFS2, and NDUFS3, whose expression levels have little impact on patient survival of any subtype of breast cancer, contain no Fe–S clusters or play no role in the main path of electron transport." (PMID 39873399, 2025).
Leigh syndrome (9 papers, 2014 to 2025). "NDUFS3 mutation is reported to cause Leigh syndrome manifested with significantly decreased CI activity." (PMID 40597361, 2025). "Two patients diagnosed with Leigh syndrome have been reported to date to carry Ndufs3 mutations, both with CNS involvement." (PMID 33148885, 2020). "Mutations affecting complex I, including in the Ndufs3 gene, cause fatal neurodegenerative diseases, such as Leigh syndrome." (PMID 33148885, 2020). "Cortex metabolomic analysis of 2.5-month-old mice showed an abnormal metabolic profile in the Ndufs3 nKO mice, which included accumulation of pyruvate, lactate, and glycolytic intermediates, consistent with clinical reports of Leigh syndrome." (PMID 33148885, 2020). "Indeed, gene silencing of NDUFS3 and mutations in the NDUFV2 gene have been shown to lead to mitochondrial dysfunction, hypertrophic cardiomyopathy, and Leigh’s Syndrome." (PMID 25216282, 2014).
Parkinson disease (6 papers, 2016 to 2025). A progressive degenerative disorder of the central nervous system characterized by loss of dopamine producing neurons in the substantia nigra and the presence of Lewy bodies in the substantia nigra and locus coeruleus. "According to KEGG, NDUFS3 is involved in molecular events associated with Parkinson disease (KEGG Pathway ID = hsa05012 - Parkinson’s disease - Homo sapiens)." (PMID 28105929, 2016). "Intriguingly, our KEGG analysis linked NDUFS3 to neurodegenerative disease pathways (e.g., Parkinson’s disease), raising questions about potential long-term neurological sequelae in GDM-exposed offspring, a hypothesis warranting longitudinal follow-up studies." (PMID 40727584, 2025). "NDUFA9, NDUFV2, and NDUFS3 are considered critical genes in oxidative phosphorylation and Parkinson’s disease, Huntington’s disease, and AD pathways." (PMID 35990086, 2022). "NDUFS3 occurs in KEGG pathways for AD, Parkinson’s disease, and Huntington’s disease (KO05010, KO05012, KO05016)." (PMID 26919393, 2016).
Alzheimer disease (4 papers, 2018 to 2025). A progressive, neurodegenerative disease characterized by loss of function and death of nerve cells in several areas of the brain leading to loss of cognitive function such as memory and language. "We targeted NDUFS3 and NDUFAF7 because these genes localize to genetic loci associated with increased risk of Alzheimer’s disease." (PMID 37171075, 2023). "The NDUFS3 and NDUFAF7 genes are encoded in loci that increase Alzheimer’s disease risk." (PMID 37171075, 2023).
colorectal cancer (4 papers, 2017 to 2025). A primary or metastatic malignant neoplasm that affects the colon or rectum. "The nuclear-encoded NDUFS3 gene was knocked-out to induce CI deficiency in mesenchymal (osteosarcoma 143B) and epithelial (colorectal cancer HCT116) cancer cells, hereafter referred to as 143B−/− and HCT−/−, with the aim to generalize our findings in two cancer models of different tissue origin." (PMID 30796225, 2019). "High expression levels of NDUFS3 were noted in colorectal cancer, gastric cancer and highly invasive breast carcinoma." (PMID 40404919, 2025). "Among other selected top co-expressed genes, PSMA2 was found to promote colorectal cancer cell proliferation and NDUFS3 has been reported to be downregulated in the ovarian cancer cell and hypothesized to promote oncogenic development." (PMID 35938038, 2022).
diabetes (4 papers, 2021 to 2024). "Taken together, this work demonstrates that PS1 negatively regulated β-cell pathogenesis and diabetes via reduction of ROS production involving the Pdia4/Ndufs3 and Pdia4/p22 cascades." (PMID 36935456, 2023). "Overall our work can be viewed as follows: excess nutrients/hyperglycemia → Pdia4 → Ndufs3 and p22phox → ROS → β‐cell failure and diabetes." (PMID 34542937, 2021). "Although the concept of ROS causing β‐cell failure is not a new concept, the participation of Pdia4 in the Ndufs3 and p22Phox pathways gives greater understanding of the progression from oxidative stress to β‐cell pathology and diabetes." (PMID 34542937, 2021).
Mitochondrial myopathy (3 papers, 2020 to 2024). "Taken together, our results show that the ablation of Ndufs3 in muscle induced a mitochondrial myopathy characterized by muscle loss and abnormal mitochondrial structure." (PMID 31916679, 2020). "Conversely, NDUFS3 gene replacement rescued muscle structure and mitochondrial in a mouse model of mitochondrial myopathy." (PMID 33072749, 2020). "The Ndufs3 smKO model recapitulated many features observed in patients with mitochondrial myopathies, such as elevated serum lactate levels and exercise intolerance." (PMID 31916679, 2020). "We generated a new model of mitochondrial myopathy by the conditional deletion of a complex I subunit (NDUFS3) in skeletal muscle." (PMID 31916679, 2020). "Furthermore, serum lactate levels from Ndufs3 smKO mice at 3, 6, and 8 months were dramatically increased, demonstrating that Ndufs3 smKO mice suffered from severe lactic acidosis, a common feature in patients with mitochondrial myopathies." (PMID 31916679, 2020). "To investigate whether gene replacement can be used as an effective strategy to treat or cure mitochondrial myopathies, we have generated a complex I conditional knockout mouse model lacking NDUFS3 subunit in skeletal muscle." (PMID 31916679, 2020).
type 2 diabetes (3 papers, 2022 to 2025). "In type 2 diabetic patients with progressive MCI or AD, plasma levels of two neuroexosome-derived mitochondrial proteins—NADH ubiquinone oxidoreductase core subunit S3 (NDUFS3) and succinate dehydrogenase complex subunit B (SDHB)—were lower than in cognitively normal patients." (PMID 40114266, 2025).
atherosclerosis (2 papers, 2023 to 2024). A disease characterized by the build-up of fatty material and calcium deposition in the arterial wall resulting in partial or complete occlusion of the arterial lumen. "Ndufs3 is likewise the catalytic core of mitochondrial complex I, which some studies have shown to be associated with atherosclerosis and chronic stress." (PMID 39775580, 2024). "Validation of significant role of NDUFB11 and NDUFS3 in atherosclerosis and chronic stress using public datasets." (PMID 37642954, 2023). "In summary, NDUFB11 and NDUFS3 are underexpressed in atherosclerosis and chronic stress, and the lower NDUFB11 and NDUFS3, the worse the prognosis." (PMID 37642954, 2023). "A heat map of the expression of core genes in the samples was plotted, and we found that the core genes (NDUFB11, NDUFS3) were lowly expressed in the atherosclerosis accompanying chronic stress samples and highly expressed in the normal samples." (PMID 37642954, 2023). "Gene expression heatmap showed that the core genes (NDUFB11, NDUFS3) were lowly expressed in samples of those with atherosclerosis accompanied by chronic stress and highly expressed in the normal samples." (PMID 37642954, 2023). "WB showed that the expression level of NDUFS3 in atherosclerosis and chronic stress was lower than that in control group." (PMID 37642954, 2023). "However, the relationship between NDUFB11 and NDUFS3 and atherosclerosis and chronic stress is unclear." (PMID 37642954, 2023). "However, the relationship between NDUFB11 and NDUFS3 and atherosclerosis and chronic stress is still unclear." (PMID 37642954, 2023). "NDUFB11 and NDUFS3 may serve as molecular targets for the precision treatment of atherosclerosis and chronic stress, thus providing a foundation of direction for mechanistic studies of atherosclerosis and chronic stress." (PMID 37642954, 2023). "Therefore, we speculate that NDUFB11 and NDUFS3 may play important roles in intracellular energy metabolism in atherosclerosis and chronic stress." (PMID 37642954, 2023). "The main results of this study are that NDUFB11 and NDUFS3 are underexpressed in atherosclerosis and chronic stress, and the lower the NDUFB11 and NDUFS3, the worse the prognosis." (PMID 37642954, 2023). "The expression level of NDUFS3, E-cadherin, BCL2, P21 and SOX9 in atherosclerosis and chronic stress were lower than that in control group." (PMID 37642954, 2023).
gastric cancer (2 papers, 2023 to 2025). A primary or metastatic malignant neoplasm involving the stomach. "However, there is no report on the evaluation of the role of NDUFS3 in gastric cancer." (PMID 37482618, 2023).
Hyperglycemia (2 papers, 2021 to 2025). An increased concentration of glucose in the blood. "The identified signature genes (RPS13, MRPS5, MRPL21, MRPL22, NDUFS3) not only unravel the molecular cascade linking maternal hyperglycemia to fetal vascular dysfunction but also offer tangible targets for diagnostic and therapeutic innovation." (PMID 40727584, 2025).
melanoma (2 papers, 2024 to 2025). A malignant, usually aggressive tumor composed of atypical, neoplastic melanocytes. "In brief, we confirmed that NDUFS3 was tightly linked to melanoma proliferation by regulating the NDUFS3-AMPK-RPPS1 signaling axis." (PMID 40404919, 2025). "The effects of the association of AMPK-PRPS1 with NDUFS3-mediated melanoma cell proliferation were examined." (PMID 40404919, 2025). "Firstly, we found that the proliferation of melanoma cells overexpressing NDUFS3 caused an increase in glucose consumption, while it downregulated the levels of lactate in the culture supernatant and the extracellular acidification rate (ECAR)." (PMID 40404919, 2025). "Taken together, these data suggested that NDUFS3-mediated melanoma progression was associated with changes in the activity of the nucleotide metabolic enzyme PRPS1." (PMID 40404919, 2025). "Collectively, these results suggested that NDUFS3 downregulates/upregulates melanoma cell proliferation by promoting/inhibiting AMPK phosphorylation and reducing/promoting PRPS1 activity." (PMID 40404919, 2025). "We further explored the effects of NDUFS3 on melanoma cell proliferation in vitro via Edu assay and colony forming ability." (PMID 40404919, 2025). "Compound C (20 μM) reversed the inhibitory effect of NDUFS3 knockdown on melanoma cell proliferation." (PMID 40404919, 2025). "Upon conducting Pearson correlation analysis, we identified a significant positive correlation between the expression levels of NDUFS3 and the Ki67 in melanoma tissues (r = 0.67, p < 0.001)." (PMID 40404919, 2025). "The upregulated or downregulated expression of NDUFS3 promoted or inhibited the proliferation of melanoma cells and melanoma xenotransplantation, respectively." (PMID 40404919, 2025). "Our data indicated that NDUFS3 was highly expressed in melanoma cells, while its overexpression promoted highly malignant behavior and poor prognosis in melanoma patients." (PMID 40404919, 2025). "No positive signals were detected in the nevi (0/10), whereas NDUFS3 expression was strongly increased in melanoma.We also calculated the expression levels of Ki67 in the same tissue chip." (PMID 40404919, 2025). "In the present study, the abundance of NDUFS3 in melanoma increased the TCA cycle and OXPHOS, while it concomitantly decreased glycolysis." (PMID 40404919, 2025). "Next, human melanoma cells A875 and SK-MEL-110 were infected with lentivirus to obtain melanoma cell lines with stable NDUFS3 overexpression (hereinafter abbreviated as NDUFS3 OE) or knockdown (hereinafter abbreviated as NDUFS3 KD)." (PMID 40404919, 2025). "An increase in OXPHOS, which is mediated by NDUFS3 in melanoma, results in an increase in the PPP, purine nucleotide metabolism and nucleic acid synthesis to sustain the proliferation of cancer cells." (PMID 40404919, 2025). "In the mitochondrial quantitative images, the melanoma cells stably transfected with NDUFS3 were marked with Deep Red mitochondrion (Mito), and morphometric quantitative measurements were acquired by Image J." (PMID 40404919, 2025). "The present study confirmed that NDUFS3 deletion induced mitochondrial fragmentation and destruction in melanoma cells." (PMID 40404919, 2025). "In contrast to these findings, the deletion of NDUFS3 in melanoma cells downregulated OXPHOS and upregulated glycolysis, which is consistent with the findings of a recent report indicating that glycolysis was upregulated in KO NDUFS3 neurons." (PMID 40404919, 2025). "We found that melanoma tumor growth was significantly promoted in mice inoculated with NUDFS3-overexpressing cell, while melanoma tumor growth was inhibited in mice bearing stable NDUFS3-knockdown cell xenografts." (PMID 40404919, 2025). "In the present study, high OXPHOS metabolic heterogeneity, which was based on the overexpression of NDUFS3, was detected in melanoma cells." (PMID 40404919, 2025).